MGMT (O-6-methylguanine-DNA methyltransferase)
Diseases named in the same sentence as MGMT in open-access papers (continued):
Sharing a sentence is not in itself a finding about the gene and the disease.
glioma (continued). "Epigenetic silencing of the MGMT (O6-methylguanine DNA methyltransferase) gene via promoter methylation impairs DNA repair mechanisms and is associated with improved treatment responses and extended overall survival in glioma patients treated with alkylating agents." (PMID 40546613, 2025). "The results showed that our proposed model could accurately predict IDH mutation and MGMT promopter methylation simultaneously in glioma patients." (PMID 40757022, 2025). "Additionally, hypermutation can develop due to exposure to DNA alkylating agents, particularly in gliomas with MGMT methylation, including those with IDH mutations." (PMID 40141375, 2025). "Then, we conduct a comprehensive analysis to answer the question of whether MRI data can be used for accurate prediction of IDH mutation status, MGMT methylation status, and survival status of gliomas by employing several large-scale MRI datasets." (PMID 41561752, 2025). "Nevertheless, other factors may play a role, as IDH1-wildtype GBM demonstrates a more significant association with MGMT status than IDH1-mutated gliomas." (PMID 40565099, 2025). "Finally, CA block combined with EfficientNetV2 model was built to simultaneously predict the IDH mutation and MGMT promoter methylation status of glioma." (PMID 40757022, 2025). "Although the association of MGMT with glioma prognosis is well-established, our results indicate that USP7 may serve as both a GBM prognostic marker and a therapeutic target, potentially functioning in association with MGMT, as suggested by our TMA IF data." (PMID 40835840, 2025). "The third alteration linked with improved survival in glioma is hypermethylation of the promoter region of MGMT, a gene encoding a DNA repair enzyme, whose low level has been associated with increased sensitivity to the alkylating agents, such as temozolomide (TMZ), used in glioma therapy." (PMID 39259492, 2024). "Certain clinical prognostic factors (such as age, gender, immunohistochemical subtypes, infiltration site, tumor size, EOR, BMI, ADC value, ECOG score, etc.)and biological prognostic factors (such as ki-67, IDH1, IDH2, MGMT, etc.)have been shown to predict the risk of recurrence in glioma patients." (PMID 38967893, 2024). "Interestingly, the co‐occurrence of IDH mutation and MGMT methylation characterizes a subtype of gliomas with a favorable prognosis and potential benefits from temozolomide, and this can potentially be predicted using radiomic models." (PMID 39252824, 2024). "MGMT promoter methylation is associated with better survival outcomes in patients with high-grade glioma and is a predictive factor for response to treatment with alkylating chemotherapy, as pointed out by major clinical guidelines in association with the classification." (PMID 38674436, 2024). "Notably, our study revealed a significant correlation between IDH1 wildtype genotype, 1p/19p co-deletion, and MGMT promoter methylation status in patients with glioma and a high-risk score." (PMID 39574472, 2024). "In light of these findings, the National Comprehensive Cancer Network (NCCN) has underscored the importance of evaluating MGMT promoter methylation status as a critical component of the molecular diagnostic workup for all high-grade gliomas, encompassing both grade 3 and grade 4 tumors." (PMID 39055560, 2024). "Therefore, the combination of IDH mutation status and MGMT promoter methylation can help stratify glioma patients into different prognostic and treatment response groups." (PMID 39100020, 2024). "MGMT promoter methylation in gliomas is associated with reduced protein expression, which may impact the expression of downstream proteins." (PMID 39759149, 2024).
glioma (continued). "However, our study finds that gliomas with edema crossing the midline tend to be associated with MGMT methylation." (PMID 38167551, 2024). "IDH1 mutant and MGMT promoter methylated gliomas were also associated with a frontal lobe location." (PMID 39767640, 2024). "However, new biomarkers are required, which, in association with the methylation of the MGMT promoter, make it possible to predict the response to temozolomide in patients with high-grade glioma." (PMID 39767683, 2024). "MGMT is implicated in DNA repair and glioma cell alkylating drug resistance." (PMID 38893240, 2024). "Data from TCGA also indicated that glioma patients with MGMT unmethylation have a high‐risk score." (PMID 39448550, 2024). "IDH1 mutant and MGMT methylated gliomas were associated with frontal lobe location." (PMID 39767640, 2024). "Interestingly, recent studies have shed light on the potential role of tumor molecular markers, such as IDH1 mutation and MGMT methylation in seizure occurrence in patients with gliomas." (PMID 36831869, 2023). "In molecular pathology, IDH mutation status, MGMT promoter methylation status and 1p19q co-deletion status are important molecular pathological features of gliomas and have a significant impact on the prognosis of glioma patients." (PMID 38022536, 2023). "The methylation of O6-methylguanine methyltransferase (MGMT) is a repair protein that can induce chemotherapy resistance by repairing DNA damage caused by TMZ, and MGMT promoter methylation can inhibit MGMT protein expression and enhance the sensitivity of glioma patients to TMZ treatment." (PMID 37889551, 2023). "Therefore, in gliomas, MGMT hypermethylation is associated with a better response to temozolomide, a DNA alkylating agent." (PMID 36831683, 2023). "Important molecular features, such as isocitrate dehydrogenases (IDH) mutations, which require testing for the workup of all gliomas, and O-6-Methylguanine-DNA methyltransferase (MGMT) promoter methylation are important clinical markers in adult-type infiltrating tumors, affecting patient outcomes." (PMID 37242509, 2023). "More widespread use of genomic DNA methylation arrays and/or ddPCR in MGMT promoter methylation assessment may be beneficial in glioma diagnostic testing, due to the apparent sensitivity of both tests." (PMID 37919784, 2023). "We included PANoptotic cluster and clinical characteristics, such as age, histology, IDH mutation, 1p/19q co-deletion, and MGMT promoter methylation into multivariate Cox regression analysis and found that PANoptotic cluster is an independent factor affecting the prognosis of glioma patients." (PMID 37501725, 2023). "Because of its predictive role in gliomas, MGMT deficiency has been advocated as a potential factor that could inform on the best sequencing of treatment in WD-NETs." (PMID 36826067, 2023). "Furthermore, the CNS5 classification incorporates molecular markers such as IDH mutation status, 1p/19q codeletion, and MGMT promoter methylation status to provide a more precise classification of gliomas." (PMID 37444408, 2023). "In the training group, we found that in the univariate analysis, TARDBP expression, PRS type, age, IDH mutation status, 1p19q codeletion status, WHO grade and MGMT status were associated with the overall survival of glioma patients, while radiation therapy, TMZ chemotherapy and sex were not related." (PMID 37147573, 2023). "Radiographically, gliomas with MGMT promoter methylation have been associated with less vasogenic edema, higher ADC values, and lower cerebral blood flow and blood volume on MR PWI, relative to unmethylated tumors according to a meta-analysis of relevant studies." (PMID 38161802, 2023). "In gliomas, the methylation status of the promoter for MGMT has been verified to be associated with glioma progression and has been identified as a biomarker to predict whether glioma patients will benefit from TMZ treatment." (PMID 36650953, 2023).
glioma (continued). "This also provides another rationale for routine NGS of glioma samples (or targeted testing for driver mutations via ddPCR) along with MGMT testing, as mutation data not only refines the histopathologic diagnosis, but also indicates how reliable the MGMT result is likely to be." (PMID 37919784, 2023). "Therefore, the status of IDH mutation and MGMT promoter methylation are important prognostic factors for glioma." (PMID 36711137, 2022). "In addition to WHO grade, it is acknowledged that IDH mutation, chromosome 1p19q codeletion, MGMT promoter methylation status, and transcriptome subtypes play a vital role in glioma progression." (PMID 35579998, 2022). "Therefore, clarifying the status of IDH mutation and MGMT promoter methylation is critical to assess the prognosis of glioma patients." (PMID 36711137, 2022). "Although several new molecules such as IDH1 mutation, MGMT promoter methylation, and 1p/19q chromosome codeletion have been applied for diagnosis and treatment in gliomas, the prognosis of patients remains unsatisfactory, which drives us to explore more effective and credible factors." (PMID 36281290, 2022). "Furthermore, we developed a nomogram based on age, IDH, grade, MGMT, and risk score to assess the 1-, 3-, and 5-year OS of glioma patients." (PMID 36358948, 2022). "MGMT epigenetic silencing has been associated with increased susceptibility to TMZ in glioma." (PMID 36125896, 2022). "Moreover, it was found that high MGMT expression was associated with a lower overall survival rate in glioma patients according to the GEPIA2 database." (PMID 35817771, 2022). "Thus, MGMT downregulation has been associated with an increased response to TMZ when combined with RT in glioma." (PMID 36125896, 2022). "Moreover, EGFR amplification was found to be present solely in IDH wildtype gliomas (26%) and TERT mutated gliomas (27%), occurring independently of MGMT promoter methylation status and being mutually exclusive with 1p/19q codeletion (LOH)." (PMID 35453544, 2022). "Moreover, the status of IDH mutation, 1p19q-codeletion, and MGMT methylation have already been verified to be essential in regard to defining glioma types and predicting the survival of patients." (PMID 36033326, 2022). "However, the critical clinical biomarker MGMT is associated with an increased immune response, as analyses revealed an upregulation of immune genes in unmethylated glioma." (PMID 34687436, 2022). "Furthermore, the level of MGMT methylation is the critical index to determine TMZ susceptibility in glioma treatment." (PMID 36146527, 2022). "In addition, CT measures were tested for differentiation of IDH mutation status and MGMT status in the subset of gliomas." (PMID 36292183, 2022). "Furthermore, we correlated PD-L1 expression with molecular glioma hallmarks such as MGMT-promoter methylation, IDH1/2 mutations, TERT promoter mutations and LOH1p/19q." (PMID 33963441, 2021). "Subsequently, we associated TERTp mutations, IDH mutations, and MGMT methylation with clinicopathological features from glioma patients and pooled analysis was performed, including sex, age, tumor location, histology, pathologic stage, and Ki-67 protein expression." (PMID 34159191, 2021). "Deep learning methods have been applied in multiple aspects of gliomas, using MRI metrics to predict long-term outcome, treatment response like pseudopregression, and tumor genetics including 1p19q codeletion, O-6-methylguanine DNA-methyltransferase promoter, and IDH mutations." (PMID 34660309, 2021). "An insertion variant of MGMT rs10659396 was identified as a novel susceptibility locus for glioma." (PMID 34544433, 2021).
glioma (continued). "Interestingly, two different groups showed that MGMT-methylated gliomas presented a lower autophagy risk score compared with MGMT-non-methylated patients." (PMID 34178638, 2021). "The role of the chemotherapeutic agent, Temozolomide remains unclear in pHGGs with the H3K27 mutation, as these gliomas are O-6-methylguanine-DNA methyltransferase (MGMT) unmethylated." (PMID 33557011, 2021). "Low MGMT unmethylation has been established to be associated with poor survival of glioma according to previous studies, while IDH mutant with 1p/19q codeletion has been observed to have better therapeutic response and clinical outcomes compared to those with non-codeletion." (PMID 33954112, 2021). "Therefore, it was widely believed that TMZ resistance in glioma patients was associated with MGMT methylation condition." (PMID 34462446, 2021). "We discovered an eQTL of MGMT rs11016798 that was associated with glioma susceptibility." (PMID 34544433, 2021). "MGMT promoter methylation status is associated with the recurrence pattern of glioma." (PMID 34784919, 2021). "Notably, BCL7A expression was negatively associated with MGMT expression in four public datasets; its expression was highly enriched in MGMT methylated glioma." (PMID 34362400, 2021). "Alternative mechanisms, such as post-transcriptional modulation of MGMT by miRNAs or the association of MGMT methylation with IDH mutation or the glioma CpG island methylator phenotype, may explain these inconsistent correlations and different outcomes." (PMID 34418985, 2021). "In this study, we investigated whether the eQTLs of MGMT identified from brain tissues confer susceptibility to glioma." (PMID 34544433, 2021). "Age, sex, IDH mutation status, ATRX mutation status, 1p/19q co-deletion status, promoter methylation status of MGMT, radiation therapy history, gliomas type, and risk score were significantly related to OS in the TCGA cohort based on the results from the univariate analysis." (PMID 34136486, 2021). "Thus IDH1/2 mutations appear to be a good survival factor in glioma, in particular when associated with MGMT methylation." (PMID 33552543, 2020). "MGMT promotor methylation is associated with favourable outcome in high-grade glioma." (PMID 33184319, 2020). "In MGMT-meth gliomas, TERT promoter mutation was correlated with a favorable survival outcome." (PMID 32957941, 2020). "Notably, the MGMT gene with promoter unmethylation was enriched in high-risk-score glioma in the TCGA dataset." (PMID 32733879, 2020). "It has been shown that textural features were associated with MGMT methylation status in particular and might be extended for different molecular subtypes in glioma." (PMID 32942564, 2020). "The average percentage methylation of the MGMT gene promoter in the ultrasonic tissue fragments taken from the core of the tumor was comparable to the values for the diagnostic biopsy (mean percentage difference 1.5 ± 0.6%, n = 5 gliomas)." (PMID 32226940, 2020). "In contrast to TERT promoter mutation, the prognostic impact of MGMT methylation was not dependent on other confounding factors including the status of TERT promoter mutation, emphasizing the important role of MGMT methylation as an independent prognostic marker in gliomas." (PMID 32957941, 2020). "In this study, we conducted a comprehensive meta-analysis to further understand whether TERT promoter mutation has any interaction with MGMT promoter methylation on overall survival (OS) of glioma patients." (PMID 32957941, 2020). "Certain genes play important roles in glioma diagnosis and treatment, such as isocitrate dehydrogenase 1 (IDHl), and mutations of such genes result in promoter methylation of O6-methylguanine-DNA methyltransferase (MGMT) and 1p/19q deletion." (PMID 33014056, 2020). "Interestingly, it has been observed that IDH-mutated gliomas frequently carry MGMT promoter methylation and are sensitive to temozolomide." (PMID 31379707, 2019).
glioma (continued). "Among grade 2 gliomas, MGMT promoter methylation was associated with a higher ELR." (PMID 31805879, 2019). "O6-methylguanine-DNA methyltransferase (MGMT) promoter methylation and its subsequent loss of protein expression has been identified to have a variable impact on clinical outcome of glioma patients indicated for chemotherapy with alkylating agents (Temozolomide)." (PMID 29712977, 2018). "Besides, the investigators have found homozygotes (TT) of C677T with low levels of folate were significantly associated with decreased methylation of MGMT in Chinese glioma patients." (PMID 30142181, 2018). "Moreover, we observed that the MGMT rs12917 polymorphism is likely to be associated with the susceptibility to glioma, which is partly in-line with the two studies on the association between DNA repair gene polymorphisms and glioma risk." (PMID 30232235, 2018). "The absence of MGMT promoter methylation is an additional negative prognostic factor in TERT mutated GBM, and assessment of MGMT promoter methylation status assists in better defining prognosis for patients with gliomas, due to the role of this feature as a predictive marker of therapeutic efficacy." (PMID 28915660, 2017). "MGMT loss may play a role as well, consistent with the resistance of MGMT unmethylatedt gliomas to alkylating agents." (PMID 26091668, 2015). "Detection of molecular glioma biomarkers such as MGMT promoter methylation, IDH1/IDH2 mutation, 1p/19q co-deletion, epidermal growth factor receptor (EGFR) amplification and EGFR variant III (EGFRvIII) expression in tumor tissue is increasingly being used in clinical care." (PMID 25720744, 2015). "In conclusion, this is the first study that investigates the immunohistochemical expression of the IMP3 protein with a correlation with other important parameters (IDH1 mutation and MGMT methylation status) and Ki67 proliferative index in a large series of high-grade gliomas." (PMID 25695077, 2015). "Several studies have shown that MGMT deficiency resulting from MGMT promoter methylation may confer increased sensitivity to alkylating agents, yet some glioma patients with MGMT promoter methylation still exhibit resistance to these drugs." (PMID 25557107, 2015). "It is hypothesised that propargyl and sulfoxide analogues deliver cytotoxic lesions to O6-guanine which cannot be removed by MGMT and both analogues have been shown to cause double DNA strand breaks leading to death in glioma cells." (PMID 24887326, 2014). "The proposed MGMT-STP27 MGMT classification model will allow investigation of distinct epigenetic features associated with MGMT silencing in the context of CIMP-positive or CIMP-negative gliomas by multidimensional analysis of respective molecular and clinical data." (PMID 22810491, 2012). "Thus, we propose that the study using the transformed astrocyte cells would be useful for identifying the mechanisms underlying MGMT regulation in tumor and for the development of rational drug combination in glioma therapies." (PMID 17547775, 2007). "Furthermore, gliomas with heterogeneous IDH mutation status or MGMT promoter methylation—critical molecular subtypes—may exhibit varying crotonylation dynamics." (PMID 40636690, 2025). "Also, increased GSK-3β expression might be associated with resistance to TMZ and poor prognosis in glioma patients by decreasing MGMT promoter methylation and thus upregulation of MGMT." (PMID 36819921, 2023).